CXCR3 (C-X-C motif chemokine receptor 3)
Diseases named in the same sentence as CXCR3 in open-access papers (continued):
Sharing a sentence is not in itself a finding about the gene and the disease.
viral infection (70 papers, 2011 to 2026). "Published data have shown that CXCR3 expression is directly linked to T-bet expression in EM cells during viral infections, and that TCF-1 controls the chemokine receptor expression in CD4 T cells and their trafficking to GvHD target organs." (PMID 36901757, 2023). "Our research involves identifying the genes encoding the CXCL9-11/CXCR3 axis, predicting the protein structure from the amino acid sequence, and exploring the regulation of gene expression as well as the response of these chemokines and their receptor to viral infections." (PMID 39301034, 2024). "In viral infections or persistent inflammation, the CD56bright NK subpopulation preferentially homes to these sites via chemokine receptors (CXCR3, CCR5, and CXCR6), which detect localized inflammatory cues." (PMID 40497938, 2025). "We use this model to confirm the necessity of CXCR3 for positioning of NK cells in the white pulp near T and B cells after virus infection." (PMID 40694683, 2025). "Frequencies of both CXCR3− and CXCR3+ circulating Tfh (cTfh) cells have been associated with antibody development in response to viral infections and vaccinations (31, –, 36), but appear to have different roles in the development of the humoral response." (PMID 39932316, 2025). "Upon acute viral infection, Tph upregulates CXCR3, TBX21, and STAT1, produces IFN-γ, to induce CXCR3 expression and neutralizing antibodies of plasmablasts." (PMID 41181158, 2025). "We confirmed the role of CXCL4:CXCR3 axis in 7D-mediated inhibition of viral infection using monocytes isolated from CXCR3−/− or CXCR3+/+ (WT) mice." (PMID 39284947, 2024). "The CXCR3 plays a protective role in dengue infection however the absence of this significantly damages the host's defense against viral infections." (PMID 38076406, 2023). "In viral infections, such as lymphocytic choriomeningitis virus and West Nile virus (WNV) encephalitis, CXCR3 deficiency can affect numbers of CNS-infiltrating CD4+ and CD8+ T cells." (PMID 36704563, 2022). "Although CXCR3 has been characterized in viral infections, further studies are needed to evaluate this cytokine’s role in metastatic cancer formation, especially in CRC." (PMID 36551555, 2022). "Multiple studies have identified CXCR3 expression by TFH cells during antibody responses to viral infection." (PMID 35812408, 2022). "In particular, the chemokine ligand CXCL10 and its receptor CXCR3 were explored in a plethora of RNA and DNA viral infections." (PMID 36366543, 2022). "Following virus infection, alveolar macrophages and neutrophils can emit a substantial amount of IP-10 to attract T cells that express the IP-10 receptor CXCR3 to the infected region, accelerating the onset, and progression of lung tissue inflammation." (PMID 35755996, 2022). "Virus infection also upregulated CXCR3 expression in CD4+ T-cells in MLN, as shown by the expansion of CXCR3+ (Student’s t-test, p = 0.002), CXCR3+CCR4+ (Student’s t-test, p = 0.007) and CXCR3+CCR5+CCR4+ CD4+ T-cell subsets (Student’s t-test, p = 0.001)." (PMID 34685494, 2021). "Studies have shown that CXCR3 and the ligands have significant roles in the oncogene of viral infection, autoimmune disease, tumor, transplant immunity, organ/tissue fibrosis, and other diseases." (PMID 34484417, 2021). "Previous studies have identified an increase in activated memory B cells expressing CXCR3 and CD11c with chronic viral infections in mice and humans, as well as with regard to HIV-specific antibody responses." (PMID 33961680, 2021). "An increase in expression of the Th1-chemokine receptor, CXCR3, on GC Tfh cells was consistent with the phenotype of cells responding to viral infection." (PMID 32818217, 2020). "The increased number of GC Tfh, GC B cells and FDCs as well as the higher relative expression of CXCR3 in mediastinal lymph nodes compared to cervical and mesenteric lymph nodes indicated an active immune response to viral infection." (PMID 32818217, 2020).
viral infection (continued). "Studies done in murine models of neurotropic viral infections indicate that B cells enter the CNS during acute viral infection with early infiltrating B cells expressing CXCR3 and CXCR5 (among others) and upregulation of the corresponding ligands in the CNS." (PMID 33224101, 2020). "This chemokine binds to the seven trans-membrane-spanning G protein-coupled receptor CXCR3, which regulates both chemotaxis and apoptosis of several immune cell types, and so can be either beneficial or detrimental to viral infection." (PMID 32324736, 2020). "Overall, results from the different animal models of viral infections suggest CNS infiltrating B cells during viral infection migrate into the CNS in a CXCR3-, CXCR5-, and CCR7-dependent manner whose ligands are also upregulated within the CNS." (PMID 33224101, 2020). "Both of these chemokines bind to the chemokine receptor CXCR3, the signaling through which has been shown to be very important in many viral infections." (PMID 31635289, 2019). "It has been reported that CXCL10 secreted from β cells activates and attracts autoreactive T cells and macrophages to the islets via CXCR3 after viral infection in human autoimmune type 1 diabetes." (PMID 30705364, 2019). "The production of cytokines and chemokines during viral infection is strongly associated with viral pathogenicity, especially, deficiency of several chemokine receptors such as CCR5 and CXCR3 promotes severity of pathogenicity against WNV infection." (PMID 30261081, 2018). "DC injection or viral infection can induce NK cell migration to draining LNs in a CXCR3-dependent fashion." (PMID 30451860, 2018). "We showed that the inhibition of BCLXL specifically induces apoptosis and impaired production of CCL5 and CXCL10, which are ligands for CCR5 and CXCR3, respectively, during in vitro and in vivo viral infections." (PMID 30261081, 2018). "This is similar to the findings regarding the role of CXCR3, which is dispensable for the control of viral infection in the periphery and in most CNS compartments but required for CD8 T cell-mediated antiviral responses specifically within the cerebellum." (PMID 26667390, 2015). "Contrarily, in children with other viral infections percentages of CXCR3+ CD8 TEM cells became significantly higher (61.94%) in convalescent phase of infection." (PMID 25013801, 2014). "Therefore, in mammals, the chemokines of the CXCL9-11/CXCR3 axis play a role in immune cell recruitment during virus infections that are involved in virus clearance." (PMID 39301034, 2024). "Moreover, recent literature has demonstrated the protective role of CXCR3 blockade against virus infection." (PMID 39001897, 2024). "CXCL10 controls viral infection and has a role in innate immune response via the recruitment and activation of natural killer cells and exerts a potent chemotactic effect on activated T lymphocytes by binding CXCR3." (PMID 38006039, 2023). "The neutralizing of CXCR3 decreases TNF-α-mediated BBB damage during viral infection." (PMID 35604176, 2022). "While CXCR3 is strongly associated with the CXCL11 chemokine, CXCL11 recruits innate natural killer cells, is involved in protective immunity by affecting the adaptive immune reaction toward tumors and viral infections, and attracts T-effector cells." (PMID 34438623, 2021). "Given that IP-10 binding to CXCR3 also activates chemotactic signaling, we speculated that IP-10 enhances viral infection through similar signaling with HIV gp120." (PMID 34447368, 2021). "Moreover, in the context of viral infection, CXCR3 on CD8+ T cells facilitates T‐cell homing to infected tissue and the ability of T cells to locate and eliminate infected cells." (PMID 31803974, 2020). "Our results strongly suggest that the CXCL10/CXCR3 axis may play a critical role in the comorbid effect of peripheral viral infections on the progression of major neuropathological diseases." (PMID 32265633, 2020).
viral infection (continued). "Moreover, CXCR3 has been found to be important in the pathogenesis of several viral infections, including influenza." (PMID 28392790, 2017). "Previous studies have shown that the CXCL10 and its receptor CXCR3 play a vital role in the inflammatory response by attracting activated T lymphocytes to the CNS following viral infections such as Lymphocytic Choriomeningitis virus, Japanese encephalitis virus, and West Nile virus." (PMID 23693026, 2013). "Since IP-10 is less sensitive to corticosteroid, we speculate that regulation of the CXCR3 ligand/CXCR3 axis would be important for regulating eosinophilic airway inflammation under specific conditions, such as viral infections." (PMID 22004287, 2011). "CXCR3 and its ligands CXCL9, CXCL10 and CXCL11 are known to regulate leukocyte recruitment during numerous viral infections." (PMID 39803542, 2024). "In viral infections, CXCL9 together with CXCL10 play a fundamental role by attracting activated T cells via CXCR3." (PMID 38664730, 2024). "Since IFN-γ is a crucial cytokine produced as part of the antiviral response mechanisms, it is likely that the Atlantic salmon CXCL9-11/CXCR3 axis genes, induced by IFN-γ, also play a role in the immune response against virus infection." (PMID 39301034, 2024). "However, CXCR3 blockade did not significantly change these pathways, suggesting that viral infection may still cause some retinal function defects." (PMID 39565860, 2024). "Following a viral infection, CXCL10/IP-10 is secreted by bronchial epithelial cells, and Th1 cells are recruited via CXCR3 to eliminate the intracellular pathogen." (PMID 24692853, 2014). "Although the ligands of CXCR3—CXCL9, CXCL10, and CXCL11—are key ISGs, it is unknown how blocking IFNAR during viral infection impacts chemokine expression for preferential formation of TSCM cells." (PMID 40062995, 2025). "Although it was initially proposed that CXCR3+ cells have reduced helper capacity compared to CXCR3− cells, CXCR3+ TFH cells have been also found to succesfully expand and secrete cytokines, particularly in response to various viral infections." (PMID 37055751, 2023). "Together, this suggests a predominant role for the CXCR3:CXCL10 axis for lung-homing upon respiratory viral infection and also in non-viral lung tissue injury." (PMID 35371005, 2022). "However, the literature suggests that in Cxcr3−/− mice memory CD8+ T cells accumulate, even after the viral infection has been cleared." (PMID 33589606, 2021). "However, recent studies have shown that CXCR3-biased cTfh cells or populations (based on PD-1 or ICOS expression) actually correlate with antibody responses and show helper function under viral infection or vaccination." (PMID 31300682, 2019). "In convalescent phase only infants with other viral infections (48.03%) managed to develop increased percentages of CXCR3+CD4 TEM, while children with RSV infection showed only tendency to develop increased percentages of CXCR3+CD4 TEM cells." (PMID 25013801, 2014). "The clonal expansion and persistence of CXCR3+ BSM post-infection suggest that IFN-g, induced by viral infection and likely produced by activated and expanded innate and Tfh cells in the tissue, may be a driving force for these developmental differences in B cell memory." (PMID 40964019, 2025). "CD8 T cells expressing CXCR3, a chemokine receptor upregulated on activated T cells, and CD127, the IL-7 receptor alpha chain expressed on cells known to become long-lived memory cells, were identified as being able to mount the strongest recall response to viral infection." (PMID 29963060, 2018). "Similar to mouse models of rickettsial and viral infections, in which CXCR3+CD8+ T cells and other immune cells contribute to pathogen clearance and pathogenesis, CXCR3 and its ligands may play complex roles in OtK-induced neuroinflammation, depending on the infection doses and disease stages." (PMID 28742087, 2017).
viral infection (continued). "Thus, spatial analyses suggest that the CXCR3 and CXCL9/10/11 axis facilitates interaction of innate and adaptive immune cells in lymphoid tissue, which may shape both the position and characteristics of memory B cells during viral infection." (PMID 40964019, 2025). "No statistically significant enrichment of Cxcr3 KO donor CD45.2+ NK cells was observed in either the white pulp (left) or T-cell zones (right) of recipient JAXBoy mice after virus infection." (PMID 40694683, 2025).
autoimmune disease (67 papers, 2011 to 2026). A disorder resulting from loss of function or tissue destruction of an organ or multiple organs, arising from humoral or cellular immune responses of the individual to their own tissue constituents. "The IFNγ-inducible chemokine CXCL10 has been implicated in T- and NKT-cell recruitment via receptor CXCR3 in autoimmune disease, various inflammatory conditions and cancer." (PMID 39007345, 2024). "Herein, we explored the function of CXCR3 in the modulation of different organ-specific autoimmune diseases in interleukin (IL)-2 receptor deficiency (CD25−/−) mice, a murine model for both cholangitis and colitis." (PMID 29868034, 2018). "C-X-C motif chemokine ligand 10 (CXCL10), also referred to as interferon gamma (IFN-γ)-inducible protein (IP-10), has been associated with the immune-pathogenesis of several autoimmune diseases such as GD via its receptor CXCR3 (chemokine (C-X-C motif) receptor 3)." (PMID 39329107, 2024). "The most notable feature of X-linked genes affected by Xist perturbation is the high number of genes involved in innate immune response (TLR7, TLR8, TLR13, TASL, and CXCR3), which have been reported to be associated with or to have a causative role in different autoimmune diseases." (PMID 38701219, 2024). "The CXCL10, also known as IFN-γ-inducible protein 10 (IP-10), through its receptor [chemokine (C-X-C motif) receptor 3 (CXCR3)], is implicated in the immune-pathogenesis of numerous autoimmune diseases, (i.e., GD and orbitopathy, type 1 diabetes, mixed cryoglobulinemia, SLE, SS, or SSc)." (PMID 35837308, 2022). "Expression of CXCR3 and its ligands is strongly associated with autoimmune diseases, such as CD." (PMID 33585005, 2020). "Unlike other somatic cells, dynamic regulation of Xist RNA and heterochromatin marks on the inactive X (Xi) in female lymphocytes results in biallelic expression of some X-linked genes, including Tlr7, Cxcr3, and Cd40l, implicated in sex-biased autoimmune diseases." (PMID 30671059, 2018). "X chromosome demethylation has been shown to result in increased CXCR3 expression in lupus, suggesting this could be a common mechanism that contributes to the female susceptibility to autoimmune diseases." (PMID 26150899, 2015). "CXCL10, a chemokine that binds to its specific receptor C-X-C motif chemokine receptor 3 (CXCR3), mobilizes and activates immune cells such as T cells, monocytes, and NK cells in specific tissues, playing a crucial role in tissue damage in autoimmune diseases." (PMID 39185418, 2024). "Among these, CXCL10 notably relies on IFN-γ for secretion, playing a pivotal role in promoting Th1 cell activation and amplifying inflammation through CXCR3-mediated feedback loops, thereby significantly influencing immune regulation in autoimmune diseases." (PMID 38900301, 2024). "This emphasizes the importance of drug design for CXCR3 in numerous diseases, such as cancer, inflammatory diseases, and autoimmune disorders." (PMID 37834457, 2023). "CXCR3+ Tregs have been shown to display unique phenotypic features and nonredundant functional properties to control Th1-related inflammation and autoimmune diseases." (PMID 36993956, 2023). "In Sjogren’s Syndrome, an autoimmune disease with a high prevalence of fatigue, anti-CXCR3 AAB levels were also diminished and negatively correlated with circulating lymphocyte counts." (PMID 36238301, 2022). "CXCL10 and its receptor CXCR3 play a role in the pathogenesis of many autoimmune diseases, and both proteins are expressed on various cells." (PMID 35269967, 2022). "Studies have shown that the chemotactic function of CXCR3 plays an important role in autoimmune diseases and cancers." (PMID 35710862, 2022). "Chemokine CXCL10 is a powerful recruiter of Th1 cells expressing CXCR3 into target tissues, which is responsible for organ-specific autoimmune diseases." (PMID 34659199, 2021).